AKIP1 (A-kinase interacting protein 1)
Description:
Enhances NF-kappa-B transcriptional activity by regulating the nuclear localization of the NF-kappa-B subunit RELA and promoting the phosphorylation of RELA by PRKACA. Regulates the effect of the cAMP-dependent protein kinase signaling pathway on the NF-kappa-B activation cascade.
Synonyms: BCA3; C11orf17
Tractability: PROTAC: ubiquitination databases record sites on it.
Gene: Protein-coding gene on chromosome 11 (8,911,113 to 8,922,406, forward strand). Ensembl gene ENSG00000166452.
Subcellular location: Nucleus
Subcellular location (Human Protein Atlas): Nucleoplasm
Gene Ontology:
Molecular function: protein binding
Biological process: regulation of non-canonical NF-kappaB signal transduction
Cellular component: nucleoplasm; nucleus
Genetic constraint (gnomAD): Loss-of-function variants: 16 observed, 18.36 expected, observed/expected ratio (o/e) 0.87, 90% interval 0.59 to 1.32. The upper end of that interval is the gene's LOEUF score, 1.32, which puts it in group 5 of 6, group 1 being the genes least tolerant of losing a copy. Missense variants: 280 observed, 253.04 expected, observed/expected ratio (o/e) 1.11, 90% interval 1 to 1.22. Synonymous variants: 119 observed, 100.26 expected, observed/expected ratio (o/e) 1.19, 90% interval 1.02 to 1.38.
Homologues: Orthologues: macaque AKIP1 (96% identical), guinea pig AKIP1 (74% identical), pig AKIP1 (74% identical), rat Akip1 (74% identical), dog AKIP1 (72% identical), mouse Akip1 (72% identical), chimpanzee AKIP1 (65% identical), rabbit AKIP1 (60% identical), tropical clawed frog akip1 (25% identical), zebrafish akip1 (25% identical).
Diseases named in the same sentence as AKIP1 in open-access papers:
AKIP1 is named in the same sentence as 35 diseases in open-access papers, as found by Europe PMC text mining. Sharing a sentence is not in itself a finding about the gene and the disease. The quoted sentences say what the papers report.
breast carcinoma (8 papers, 2013 to 2023). "A kinase interacting protein 1 (AKIP1) is a small 23 kDa protein originally identified as a breast cancer associated gene (BCA3)." (PMID 24236204, 2013). "This protein has been identified in breast cancer tissues previously by Kitching, Li, and the particular expression level of AKIP1 seems to affect the NF-kB cascade by regulating the mode of PKA signaling." (PMID 31945087, 2020). "Stage 3 breast cancer samples contained the inhibitor of nuclear factor kappa-B (NF-kB) kinase-interacting protein (AKIP1)." (PMID 31945087, 2020). "Overexpression of A‐kinase‐interacting protein 1 (AKIP1) has been reported in prostate and breast cancers." (PMID 32401379, 2020). "Due to its function, AKIP1 has previously been reported to act as a potential oncogenic protein in various cancers such as esophageal squamous cell carcinoma, breast carcinoma, non-small-cell lung cancer and colorectal cancer." (PMID 35096829, 2021). "Additionally, the AKIP1 is overexpressed in breast cancer and is related to poor prognosis of survival." (PMID 30706161, 2019). "Previous work has investigated the effects of AKIP1 in breast cancer cells, but to date, this has not been investigated in myometrium." (PMID 34166397, 2021).
cervical cancer (6 papers, 2020 to 2022). A primary or metastatic malignant neoplasm involving the cervix. "For instance, it is proposed that AKIP1 induces the nuclear factor kappa-B (NF-κB)-dependent chemokines to promote angiogenesis and tumor growth in cervical cancer." (PMID 35965570, 2022). "By binding to the endothelial receptor CXCR2, these chemokines are involved in endothelial tube formation as well as in the proliferation of cervical cancer cells and in the clone-formation that is induced by the overexpression of AKIP1." (PMID 34833360, 2021). "Additionally, AKIP1 interacts with Tap73 to modulate the radiotherapy sensitivity of cervical cancer cells." (PMID 35965570, 2022). "Moreover, it was shown that the A-kinase-interacting protein 1 (AKIP1) induced NF-κB-mediated EMT by downregulating PTEN in cervical cancer." (PMID 35954450, 2022). "AKIP1 in cervical cancer cells stimulates the expression of CXCL1, CXCL2, and CXCL8." (PMID 34833360, 2021). "Besides, AKIP1 inhibition results in reduction in tumor growth and angiogenesis in cervical cancer mouse models and decrease in proliferation in cervical cancer cells." (PMID 35355804, 2021). "Therefore, AKIP1 is critical to the angiogenesis and growth of cervical cancer by increasing levels of the NF-κB-dependent chemokines CXCL1, CXCL2, and CXCL8." (PMID 34833360, 2021). "Nevertheless, the clinical potential of AKIP1 during the development of cervical cancer (CC) remains unclear." (PMID 32401379, 2020).
cardiac hypertrophy (4 papers, 2013 to 2023). "Next, we sought to determine the switch in molecular mechanisms underlying AKIP1-induced physiological cardiac hypertrophy, focused on the Akt-C/EBPβ-CITED4 pathway." (PMID 36899057, 2023). "In conclusion, our studies revealed that the signalling adaptor AKIP1 is a novel regulator of cardiomyocyte elongation and physiological cardiac hypertrophy, which is associated with the activation of two growth signalling pathways." (PMID 36899057, 2023). "We then determined the localisation of AKIP1 in the cardiomyocyte, which could potentially explain a switch in transcription factors underlying the exercise-induced cardiac hypertrophy." (PMID 36899057, 2023). "To define the contribution of AKIP1 to physiological cardiac hypertrophy, we compared the cardiac response to four weeks of voluntary wheel running exercise between AKIP1-TG and WT mice." (PMID 36899057, 2023). "While exercise parameters were comparable between genotypes, exercise-induced cardiac hypertrophy was augmented in AKIP1-TG vs. WT mice as evidenced by an increase in HW/TL by weighing scale and in LV mass on MRI." (PMID 36899057, 2023). "Exercise performance was comparable between genotypes, whereas exercise-induced cardiac hypertrophy was significantly increased in AKIP1-TG mice." (PMID 37914850, 2023). "Together, these data suggest that the marked increase in cardiac hypertrophy observed in AKIP1-TG mice is adaptive in nature." (PMID 36899057, 2023). "In fact, left ventricular end diastolic volume (LVEDV) was numerically lower in AKIP1-TG mice after exercise, suggesting that the observed eccentric cardiac hypertrophy is adaptive in nature." (PMID 36899057, 2023). "In this study we aimed to identify if AKIP1 also affected other aspects of physiological cardiac hypertrophy, specifically the mitochondrial adaptation to exercise." (PMID 37914850, 2023). "While cardiac structure and function were comparable between sedentary AKIP1-TG and WT mice, exercise-induced cardiac hypertrophy was substantially enhanced by AKIP1." (PMID 36899057, 2023). "In a previous gene array study, we identified AKIP1 as a differentially expressed gene in cardiac hypertrophy." (PMID 24169435, 2013). "Myocardial expression of AKIP1 is increased in physiological hypertrophy and overexpression of AKIP1 induces hypertrophy in cultured cardiomyocytes that resembles physiological cardiac hypertrophy in vivo." (PMID 36899057, 2023). "We next aimed to corroborate whether the augmented exercise-induced cardiac hypertrophy in AKIP1-TG mice was adaptive in nature." (PMID 36899057, 2023). "Our discovery that AKIP1 stimulates physiological cardiac growth in vivo, by activating two distinct but complementary physiological signalling pathways, provides strong evidence that AKIP1 is a bona fide regulator of physiological cardiac hypertrophy." (PMID 36899057, 2023). "Accordingly, we tested the hypothesis that cardiomyocyte-specific overexpression of AKIP1 in mice promotes cardiac hypertrophy in response to voluntary exercise in vivo." (PMID 36899057, 2023). "The underlying molecular mechanisms of the mitochondrial changes should be further explored, and future studies should reveal whether these findings are essential for AKIP1-induced physiological cardiac hypertrophy." (PMID 37914850, 2023). "As expected, LY294002 completely blocked AKIP1-induced cardiac hypertrophy." (PMID 24169435, 2013). "In the present study we show that AKIP1 protein levels are elevated in cardiac hypertrophy." (PMID 24169435, 2013).
gastric cancer (4 papers, 2019 to 2022). A primary or metastatic malignant neoplasm involving the stomach. "Above all, there is also correlation between AKIP1 and gastric cancer, which elucidates that it is involved in tumor progression through the modulation of Slug-induced epithelial–mesenchymal transition, which then enhances growth and metastasis of the tumor." (PMID 35355804, 2021). "Our results elucidated that AKIP1 promoted migration and stemness of gastric cancer cells, suggesting that it also acted as a promoter of tumor progression in gastric cancer." (PMID 35355804, 2021). "As NF‐κB can modulate the EMT phenotype in gastric cancer, it is thought to be related to the AKIP1‐induced EMT." (PMID 32401379, 2020). "Other methods including stably transfected against AKIP1 into gastric cancer cells, wound healing, transwell assays, CCK‐8, colony formation, qRT‐PCR and Western blot in vitro and tumorigenesis in vivo were also performed." (PMID 31020809, 2019). "In the present study, we tried to explore the role of AKIP1 in gastric cancer cells under hypoxia and its probable downstream pathways and found that, first of all, the cell invasion, CD133+ cell percentage, and sphere number/1,000 cells were promoted in gastric cancer cells under hypoxia." (PMID 35355804, 2021). "Hence, the present study aimed to investigate the effect of AKIP1 on cell invasion and stemness in gastric cancer under hypoxia, and its interaction with hypoxia-inducible factor 1 subunit alpha (HIF-1α) and β-catenin pathways." (PMID 35355804, 2021). "Therefore, this study aimed to explore this topic to uncover AKIP1’s role in gastric cancer under hypoxia." (PMID 35355804, 2021). "These suggested that AKIP1 might be engaged in the hypoxia-induced cell invasion and stemness in gastric cancer." (PMID 35355804, 2021). "The clinical significance and biological role of AKIP1 in gastric cancer (GC) is, however, still elusive." (PMID 31020809, 2019). "AKIP1 was upregulated in gastric cancer cells under hypoxia, and AKIP1 enhanced cell invasion, CD133+ cell proportion, and sphere number/1,000 cells in gastric cancer cells under hypoxia." (PMID 35355804, 2021). "AKIP1 promotes cell invasion and stemness via activating HIF-1α and β-catenin signaling pathways in gastric cancer under hypoxia condition." (PMID 35355804, 2021). "A-Kinase interacting protein 1 (AKIP1) relates to gastric cancer growth, metastasis, and prognosis, while its regulation on gastric cancer invasion and stemness under hypoxia microenvironment is not reported." (PMID 35355804, 2021). "Furthermore, the rescue experiments disclosed that HIF-1α and β-catenin pathways overexpression reduced the effects of AKIP1 knockdown on invasion, CD133+ cell proportion, and sphere number/1,000 cells in gastric cancer cells under hypoxia." (PMID 35355804, 2021). "Gastric cancer cell lines AGS and MKN45 were cultured under hypoxia condition, then transfected with AKIP1 or negative control (NC) overexpression plasmid or AKIP1 or NC knockdown plasmid." (PMID 35355804, 2021).
glioma (4 papers, 2022 to 2025). A benign or malignant brain and spinal cord tumor that arises from glial cells (astrocytes, oligodendrocytes, ependymal cells). "In previous studies, the AKIP1 gene and the protein it encoded were reported as novel biomarkers and as involved in the progression and prognosis of patients with cancers, including glioma, multiple myeloma, and thyroid carcinoma." (PMID 39766778, 2024). "In the present study, we aimed to investigate if AKIP1 was involved in the development of glioma and uncovered the underlying mechanism, which might open up new routes for the treatment of glioma." (PMID 35111846, 2022). "Finally, DLG2 was further downregulated in glioma cells to detect the association between AKIP1 and DLG2 in the cellular functions of glioma." (PMID 35111846, 2022). "DLG2 inhibited the epithelial-mesenchymal transition of glioma cells by regulating the AKIP1/DLG2 pathway." (PMID 39856747, 2025). "Then, we tested if AKIP1 exerted effects on the T98G cell functions to affect the progression of glioma by regulating DLG2." (PMID 35111846, 2022). "To conclude, this study presents evidence that AKIP1 silencing suppresses the progression of glioma via targeting DLG2." (PMID 35111846, 2022). "The purpose of this study was to discuss the important role of A kinase-interacting protein 1 (AKIP1) in glioma and reveal the potential mechanism." (PMID 35111846, 2022). "It was demonstrated that AKIP1 exhibited a high level in glioma cells, and interference of AKIP1 led to reductions in the proliferation, migration, invasion, and EMT of glioma cells." (PMID 35111846, 2022). "Recent report has considered AKIP1 as an independent predictor factor for malignant glioma by virtue of high AKIP1 expression presented in most of glioma patients." (PMID 35111846, 2022). "Among these glioma cells, T98G cells, which exhibited the highest levels of AKIP1, were chosen for the following experiments." (PMID 35111846, 2022). "In the present study, overexpressed AKIP1 was also noted in a myriad of glioma cell lines, which was consistent with the public recognition that AKIP1 might exert an oncogenic role in tumor cells." (PMID 35111846, 2022). "Subsequently, the effects of AKIP1 on the cellular functions of glioma were investigated." (PMID 35111846, 2022). "The latest statistics, which illustrated the negative association of AKIP1 with overall survival of glioma patients, elucidated the potential of AKIP1 to be a novel biomarker for the treatment of glioma." (PMID 35111846, 2022). "CCLE website predicted that the expression of AKIP1 was upregulated in glioma cells." (PMID 35111846, 2022). "Importantly, we have noted the significance of AKIP1 in glioma which may be regarded as a potent molecular marker for glioma." (PMID 35111846, 2022). "This mechanistic study may open up new routes for the application of AKIP1 to glioma therapy." (PMID 35111846, 2022). "Humanbase demonstrated the interplay between AKIP1 and DLG2, and we further employed CGGA database to discover that AKIP1 was in negative association with DLG2 in primary and recurrent glioma." (PMID 35111846, 2022). "AKIP1, which was predicted by CCLE website to present abnormally high levels in glioma cells, was expected to act as a novel target for the diagnosis and treatment of glioma." (PMID 35111846, 2022). "Notably, the inhibitory impacts of AKIP1 insufficiency on the proliferation, migration, invasion, and EMT process of T98G cells were reversed by silencing of DLG2, which indicated that AKIP1 modulated these cell functions so as to affect glioma development by targeting DLG2." (PMID 35111846, 2022). "In addition, CGGA database indicated the negative correlation between the expression of AKIP1 and DLG2 in primary and recurrent glioma." (PMID 35111846, 2022).
lymph node metastasis (3 papers, 2019 to 2022). "The elevated AKIP1 expression in primary tumours was related to lymph node metastasis in CC patients." (PMID 32401379, 2020). "Next, the relationship between AKIP1 and clinicopathological variables demonstrated that AKIP1 was closely related with tumour size, T stage, pTNM stage and lymph node metastasis respectively (P < 0.05), suggesting that AKIP1 might function importantly in GC progression and metastasis." (PMID 31020809, 2019).
myocardial ischemia (3 papers, 2018 to 2023). A disorder of cardiac function caused by insufficient blood flow to the muscle tissue of the heart. "The AKIP1 protein is involved in cardioprotective effects during in vitro and ex vivo myocardial ischemia." (PMID 30181740, 2018).
esophageal squamous cell carcinoma (2 papers, 2021). Esophageal squamous cell carcinoma (ESCC) is a type of esophageal carcinoma (EC) that can affect any part of the esophagus, but is usually located in the upper or middle third. "Moreover, a study revealed that in esophageal squamous cell carcinoma, in vivo and in vitro, AKIP1 overexpression enhances angiogenesis and lymphangiogenesis, and AKIP1 downregulation exerts the opposite effects." (PMID 35355804, 2021).
heart failure (2 papers, 2013 to 2023). Inability of the heart to pump blood at an adequate rate to meet tissue metabolic requirements. "Conditions that trigger hypertrophy and heart failure formation, as well as ischemia/reperfusion, trigger AKIP1 expression in the heart." (PMID 24236204, 2013). "Together, these findings suggest that AKIP1 regulates the physiological cardiac growth response and serves as a potential therapeutic target to induce physiological growth in a pathological setting such as heart failure." (PMID 37914850, 2023).
hepatocellular carcinoma (2 papers, 2021). A malignant tumor that arises from hepatocytes. "Recent studies in hepatocellular carcinoma (HCC) showed that increased AKIP1 and PRC1 expression leads to activation of Wnt signaling, which promotes early HCC recurrence." (PMID 34446021, 2021). "A previous study illustrates that AKIP1 promotes the malignant behaviors of hepatocellular carcinoma (HCC) cells via activating protein kinase B (AKT) and nuclear factor-kappa B (NF-kB) translocation." (PMID 35355804, 2021).
myocardial infarction (2 papers, 2013). Gross necrosis of the myocardium, as a result of interruption of the blood supply to the area, as in coronary thrombosis. "We showed that AKIP1 gene expression is upregulated by pressure overload and post-myocardial infarction and is predominantly expressed in cardiomyocytes in the heart." (PMID 24169435, 2013).
prostate carcinoma (2 papers, 2014 to 2022). A carcinoma that arises from epithelial cells of the prostate gland. "A kinase-interacting protein 1 (AKIP1), a 23 kDa protein, was originally discovered in breast and prostate cancer cell lines by mRNA screens." (PMID 35111846, 2022). "Breast carcinoma-associated protein 3 (BCA3, a proline-rich protein also known as A-kinase interacting protein or AKIP1) was first identified and characterized in breast and prostate cancer cell lines." (PMID 24886575, 2014).
anaplastic thyroid carcinoma (1 paper, 2022). "A-kinase interacting protein 1 (AKIP1) promotes tumor progression and chemoresistance in several malignancies; meanwhile, it is related to higher tumor size and recurrence risk of papillary thyroid carcinoma, while the role of AKIP1 in anaplastic thyroid carcinoma (ATC) is unclear." (PMID 35965570, 2022).
chorioamnionitis (1 paper, 2021). A morphologic finding indicating inflammation of the fetal sac membranes. "Similarly, AKIP1 levels are raised in myometrial samples from 3 phenotypically distinct causes of preterm labour, chorioamnionitis, idiopathic and stretch-induced." (PMID 34166397, 2021). "In chorioamnionitis-associated PTL and to a lesser extent in idiopathic-PTL, AKIP1 mRNA levels were reduced and protein levels increased." (PMID 34166397, 2021). "In the myometrial samples from women with in early preterm labour due to chorioamnionitis, twins and idiopathic preterm labour, AKIP1 mRNA levels varied, but protein levels were consistently increased when compared to samples from women delivered preterm but not in labour." (PMID 34166397, 2021).
coagulation disorder (1 paper, 2022). "Taken together, these results demonstrated that VP35 causes coagulation disorder in mice through the AKIP1-PKA-CREB1 pathway." (PMID 35474062, 2022).
ischemia (1 paper, 2020). A hypoperfusion of the BLOOD through an organ or tissue caused by a PATHOLOGIC CONSTRICTION or obstruction of its BLOOD VESSELS, or an absence of BLOOD CIRCULATION. "It is considered a regulator cardiac stress adaptation, as overexpression of AKIP1 in the cardiac tissues, shields the heart from ischemia/reperfusion and refined heart function." (PMID 32401379, 2020).